ADAMTS6 (ADAM metallopeptidase with thrombospondin type 1 motif 6)
Diseases named in the same sentence as ADAMTS6 in open-access papers (continued):
Sharing a sentence is not in itself a finding about the gene and the disease.
squamous cell carcinoma (2 papers, 2024 to 2025). A carcinoma arising from squamous epithelial cells. "The survival analysis demonstrated that a lower ADAMTS6 expression in squamous cell carcinoma was associated with extended survival." (PMID 38339175, 2024). "However, among squamous cell carcinoma patients, a lower expression of ADAMTS6 was associated with longer survival compared to those with higher expression (p = 0.0224)." (PMID 38339175, 2024). "Squamous cell carcinoma was characterized by a lower mRNA level of the ADAMTS6 gene than adenocarcinoma (p = 0.0329)." (PMID 38339175, 2024). "Treatment with TGF-β1 at a concentration of 2 ng/mL increased ADAMTS6 expression in H1975 LUAD cells after 24–48 h (log2FC ≥ 1.3) and in SK-MES-1 squamous cell carcinoma cells after 6–48 h (log2FC ≥ 1.2)." (PMID 41465277, 2025).
stomach cancer (2 papers, 2021 to 2022). "A study utilizing The Cancer Genome Atlas (TCGA) and RNA-seq data revealed that high ADAMTS6 expression in gastric cancer patients associated with poor clinical outcome and reliably predicted overall survival." (PMID 36339722, 2022). "Our study revealed that ADAMTS6 is a tumor promoter, whose overexpression mediates occurrence, proliferation, invasion, or metastasis of stomach tumor, thus leading to a high mortality." (PMID 33851708, 2021). "Therefore, elevated levels of ADAMTS6 in gastric cancer is a tumor promoter and mediates occurrence, tumor cell proliferation, invasion and metastasis that leads to increased mortality." (PMID 36339722, 2022). "Furthermore, ADAMTS6 expression is correlated with tumor stage and histological grade and shown to promote the development and occurrence of stomach cancer." (PMID 36339722, 2022). "In addition, the ADAMTS6 gene was shown to promote the occurrence and development of stomach cancer." (PMID 33851708, 2021).
age-related macular degeneration (1 paper, 2023). Age-related loss of vision in the central portion of the retina (macula), secondary to retinal degeneration. "ADAMTS genes (ADAMTS1, ADAMTS6 and ADAMTS9) may associate with age-related macular degeneration and MAP1B was higher expression in the macula of human eye." (PMID 37389979, 2023).
bladder urothelial carcinoma (1 paper, 2025). "Reduced ADAMTS6 gene transcript levels have also been observed in bladder urothelial carcinoma (BLCA), kidney chromophobe (KICH), kidney renal clear-cell carcinoma (KIRC), kidney renal papillary-cell carcinoma (KIRP), skin cutaneous melanoma (SKCM), and uterine corpus endometrial carcinoma (UCEC)." (PMID 39940703, 2025).
cervical cancer (1 paper, 2020). A primary or metastatic malignant neoplasm involving the cervix. "Hypermethylation of ADAMTS6 is identified in multiple cancers, and its methylation level continuously decreased in mCHG, while LMX1A continuously increased in mCHG and serve as a DNA methylation marker in cervical cancer." (PMID 32258002, 2020).
esophageal cancer (1 paper, 2020). A primary or metastatic malignant neoplasm involving the esophagus. "ADAMTS6 is highly expressed in esophageal cancer and is an independent marker of its prognosis." (PMID 32884571, 2020).
lung squamous-cell carcinoma (1 paper, 2025). "The ADAMTS6 gene was found to demonstrate significantly lower expression in lung squamous-cell carcinoma than in normal cells (p < 0.05)." (PMID 39940703, 2025). "Statistically significant differences in promoter methylation were observed for the ADAMTS6 gene with regard to the UALCAN data, particularly among patients with squamous-cell lung cancer." (PMID 39940703, 2025). "The findings indicate significantly higher ADAMTS6, ADAMTS9, and ADAMTS12 promoter methylation in the tissue affected by cancer compared with normal tissue in patients with squamous-cell lung cancer (p < 0.001)." (PMID 39940703, 2025).
omphalocele (1 paper, 2022). Omphalocele is an embryopathy classified in the group of abdominal celosomias and is characterized by a large hernia of the abdominal wall, centered on the umbilical cord, in which the protruding viscera are protected by a sac. "Adamts6-/-;Adamts10-/- embryos demonstrated markedly more severe external anomalies than Adamts6-/- mutants including subcutaneous hemorrhage, micrognathia and an omphalocele, along with more severe forelimb and hindlimb dysmorphology." (PMID 35503090, 2022).
osteoporosis (1 paper, 2023). A condition of reduced bone mass, with decreased cortical thickness and a decrease in the number and size of the trabeculae of cancellous bone (but normal chemical composition), resulting in increased fracture incidence. "Second, our negative results could not totally deny the potential of ADAM12, ADAM19, ADAM23 and ADAMTS6 as biomarkers for osteoporosis due to the weakness of MR analysis in identifying non-linear relationship." (PMID 37468870, 2023).
osteosarcoma (1 paper, 2022). A usually aggressive malignant bone-forming mesenchymal neoplasm, predominantly affecting adolescents and young adults. "ADAMTS6 expression was downregulated, as shown by RNA-seq and validated by qRT-PCR, in adipose-derived stem cells undergoing osteogenesis and a genome wide association study (GWAS) identified ADAMTS6 as a promising, but not yet genome-wide significant, susceptible loci for osteosarcoma." (PMID 36339722, 2022).
ovarian carcinoma (1 paper, 2024). A malignant neoplasm originating from the surface ovarian epithelium. "TAMs export miR-221-3p, which targets the expression of A disintegrin and metalloproteinase with thrombospondin motifs 6 (ADAMTS6) in ovarian cancer." (PMID 39802952, 2024).
preeclampsia (1 paper, 2021). Preeclampsia is a hypertensive disorder of pregnancy that is characterized by new-onset hypertension with proteinuria presenting after 20 weeks of gestation, and depending on mild or severe forms may initially present with severe headache, visual disturbances, and hyperreflexia. "Similarly, the expression of SDC1, NPPB (natriuretic peptide B), GDF15 (growth differentiation factor 15), and ADAMTS6 (ADAM metallopeptidase with thrombospondin type 1 motif 6) all had a lower expression in our experimental exposures, and all are lower in preeclampsia." (PMID 34150771, 2021).
rectal cancer (1 paper, 2020). A primary or metastatic malignant neoplasm that affects the rectum. "Notably, ADAMTS6 displays the opposite trend in expression in colon and rectal cancer." (PMID 32884571, 2020).
schwannoma (1 paper, 2025). A benign, usually encapsulated slow growing tumor composed of Schwann cells. "Other notable ECM-related genes include that we identified in our analysis with less evidence in schwannoma included: ITGA1, POSTN, SPP1, ID3, ADAMTS6." (PMID 40585242, 2025).
tumor (17 papers, 2016 to 2025). "Together, these data show that ADAMTS6 overexpression is associated with G3 tumor tissues samples in GC patients, P=0.01." (PMID 33851708, 2021). "Studies in non-tumor cells have shown that ADAMTS6 can activate the latent transforming growth factor beta 1 (TGF-β1) and downstream SMAD2/3 pathway, whose role in EMT has been demonstrated in numerous studies." (PMID 41465277, 2025). "Seven genes were associated with recurrence and progression: ADAMTS6, CRMP1, PTTG, ASK, CCNB1, AURKB, and CENPE, while ADAMTS6, CRMP1, ASK, CCNB1, and CENPE were also associated with tumor recurrence and progression." (PMID 41303810, 2025). "With the dual role of ADAMTS6 as either cancer tumor suppressor and pro-tumoral agent, analysis and correlation studies are of key importance to decipher the precise role of ADAMTS6 in cancer development." (PMID 36339722, 2022). "Further studies that add to current in vitro data, such as inhibiting or enhancing ADAMTS6 in tumor mouse models is warranted to study these cancers in depth to reveal therapeutic potential." (PMID 36339722, 2022). "The role of ADAMTS6 in tumor development is unclear, as it seems to act as either a tumor suppressor or pro-tumoral agent, depending on the cancer type." (PMID 36612109, 2022). "ADAMTS6 expression is largely correlated with tumor stage, targeted molecular therapy, radical resection, radiation therapy, and histological grade of the GC." (PMID 33851708, 2021). "Correlative analysis revealed that, in men, CTAG2 expression was strongly correlated with known lactotroph tumor aggressiveness markers implicated in the cell cycle (CENPE, AURKB, CCNB1, ADAMTS6)." (PMID 30555413, 2018). "In conclusion, we demonstrated that ADAMTS6 suppresses tumorigenesis by inhibiting cells migration and invasion in vitro and tumor growth in vivo via the ERK pathway, thereby demonstrating its protective function in BC." (PMID 27542224, 2016). "Tumor volumes were significantly lower in the ADAMTS6 overexpression group and higher in the downregulated group (p < 0.01)." (PMID 27542224, 2016). "The fact that ADAMTS6 independently predicts favorable outcomes provides additional evidence for the tumor suppressor function of ADAMTS6 in BC." (PMID 27542224, 2016). "Compared with vector controls, overexpressed or downregulated ADAMTS6 significantly repressed or enhanced tumor growth, respectively, in nude mice." (PMID 27542224, 2016). "Together, these data demonstrate that ADAMTS6 inhibits tumor development by regulating the ERK pathway via binding of miR-221-3p." (PMID 27542224, 2016). "Besides, our analysis of the ADAMTS genes expression in different tumor stages and histologic grades showed that the ADAMTS6 expression was significantly different in G1/G2 and G3 tumor tissues." (PMID 33851708, 2021). "ADAMTS6 suppressed tumor progression via the ERK signaling pathway and might serve as a prognostic marker in BRCA." (PMID 33179733, 2020). "A further study utilizing qRT-PCR analysis showed increased expression of ADAMTS6 in aggressive and aggressive-invasive prolactin pituitary tumors, as compared to non-invasive tumors, and further showed that this increase in expression corelated with tumor recurrence and progression." (PMID 36339722, 2022). "ADAMTS1 functions dualistically: it can suppress tumor growth but also potentially support invasion via the Notch1-SOX2 pathway, whereas ADAMTS6 has unambiguously pro-oncogenic properties." (PMID 41304780, 2025). "Based on data collected from the UALCAN database, differences in the ADAMTS6, ADAMTS9 and ADAMTS12 gene expression levels were also assessed between tumor tissue and normal tissue." (PMID 38339175, 2024). "The second aim of the project was to evaluate the expression of the ADAMTS6, ADAMTS9 and ADAMTS12 genes in the tumor tissue samples." (PMID 38339175, 2024).
tumor (continued). "A survival analysis was conducted based on the ADAMTS6, ADAMTS9 and ADAMTS12 expression in tumor tissue using data gathered from the external Kaplan–Meier Plot database." (PMID 38339175, 2024). "ADAMTS6, like many other ADAMTS family members, has a pro- or anti-tumor role in various types of cancer, spanning several organ systems." (PMID 36339722, 2022). "In the cDNA microarray dataset analyzed with GEO2R, expression levels of ADAM32, ADAMTS6, and ADAM9 in HBL tumor tissues were 1.5-fold higher than in NCL." (PMID 36230656, 2022). "Many genes in these chromosome regions, such like ERLIN2 (amp 8p11.23), VAV2 (del 9q34.2), ADAMTS6 (del 5q12.3) and NCS1 (del 9q34.11), are known to be related with tumor invasion and metastasis." (PMID 33193655, 2020). "The presented results indicate the significant correlation between the CXCL12, CXCR4, CXCL8/CXCR2, M-CSF, MMP-2, MMP-9 ADAM17, ADAMTS-6, and CLDN7 levels and tumor stage, as well as the clinicopathological parameters of OC, such as the presence of lymph node and/or distant metastases." (PMID 38673838, 2024). "While it was not shown to be correlated with the patient’s age, sex or tumor size, ADAMTS6 staining was corelated with clinical stage, metastasis, recurrence and poor overall survival." (PMID 36339722, 2022). "A tumorigenesis assay showed subcutaneous tumor growth in nude mice injected with MCF-7 cells overexpressing or lacking ADAMTS6 expression." (PMID 27542224, 2016). "Hence, we inferred that ADAMTS6, as another member of the same subgroup, might affect EMT and AKT/NF-κB in tumor as well." (PMID 33063817, 2020). "By analyzing clinicopathological parameters, we found that ADAMTS6 expression did not vary in LUAD tumors from patients of different ages, genders, tumor stages, and TNM stages." (PMID 41465277, 2025). "A previous study on the effect of AGR2 overexpression on drug resistance also found ADAMTS6 expression to be reduced in NSCLC; however, the experiment did not specify the histological subtype of the studied tumor." (PMID 39940703, 2025).
cancer (10 papers, 2016 to 2025). A tumor composed of atypical neoplastic, often pleomorphic cells that invade other tissues. "In addition, ADAMTS6 has been linked to numerous disease settings including several types of cancer." (PMID 36339722, 2022). "Disintegrin and metalloproteinase with thrombospondin motifs 6 (ADAMTS6) is an extracellular protease important for cardiac and muscular development but has recently been shown to participate in cancer progression." (PMID 41465277, 2025). "In some instances, ADAMTS6 was shown to be either upregulated or downregulated in the same cancer type based on microarrays, clinical samples, and in vitro assays." (PMID 36339722, 2022). "Knockdown of ADAMTS6 in this cancer cell line resulted in delayed wound healing and decreased cell migration." (PMID 36339722, 2022). "The main processes that ADAMTS6 has been identified to participate in will be discussed in the following sections, spanning embryology through cancer and other disease settings." (PMID 36339722, 2022). "Shown to be abundantly apparent in the cytoplasm and nucleus, ADAMTS6 showed strong staining in the cancer cell invasive front." (PMID 36339722, 2022). "Some studies also demonstrated that the ADAMTS6 gene was significantly upregulated in cancer cells and stromal cells." (PMID 31273229, 2019). "Similarly, miR-221-3p, found upregulated in several cancer types, was found to suppress the expression of ADAMTS6 in MCF-7 cells." (PMID 38948119, 2024). "In the cancer cell lines surveyed, ADAMTS6 protein and mRNA levels were downregulated." (PMID 36339722, 2022). "However, ADAMTSs regulate cancer in a complex manner that involves multiple mechanisms; thus, more mechanistic studies are required to better understand the role of ADAMTS6 in human cancer." (PMID 27542224, 2016). "Indeed, in CRC, ADAMTS6 promotes EMT to drive cancer cell migration and invasion." (PMID 38948119, 2024). "Thus, as with the role of ADAMTS6 in cancer, the role of circADAMTS6 in disease is tissue specific." (PMID 36339722, 2022). "The differential methylation region (DMR) pattern demonstrated by ADAMTS6, ADAMTS9, and ADAMTS12 is a useful tool for distinguishing normal from cancer cells." (PMID 39940703, 2025). "Different transcript levels of ADAMTS6, ADAMTS9, and ADAMTS12 are observed in various types of cancer, which points to the problematic part played by these proteases in the pathogenesis of proliferative diseases." (PMID 39940703, 2025). "The bioinformatic analyses found the presence of a distinct DMR pattern among ADAMTS6, ADAMTS9, and ADAMTS12 to be a useful tool for distinguishing normal cells from cancer cells." (PMID 39940703, 2025). "Gene set enrichment analysis showed that high ADAMTS6 mRNA levels led to elevated VEGF and TNF pathway expression amongst other cancer-related pathways." (PMID 36339722, 2022). "The gene expression data available in the databases indicated differences between tumors and normal tissue with regard to the regulation of ADAMTS6, ADAMTS9, and ADAMTS12, which may be related to their different roles in cancer pathogenesis." (PMID 39940703, 2025). "White the overall majority of studies show that increased expression of ADAMTS6 is pro-cancer and correlates with a negative outcome, there are a few exceptions noted." (PMID 36339722, 2022).
cancer (continued). "We also identified the top 1 GEAR in individual cancer types, such as TLL1 (BLCA), PGK1 (BRCA), RFXANK (CESC), DPP7 (COAD), VWA8 (KIRC), SCMH1 (LGG), HILPDA (LIHC), TLE1 (LUAD), CD151 (LUSC), ANKRD13A (OV), SOCS2 (PAAD), DRG2 (PRAD), ADAMTS6 (STAD), PSMB8 (THCA), ASS1 (UCEC)." (PMID 41404730, 2025).
adenocarcinoma (1 paper, 2024). A common cancer characterized by the presence of malignant glandular cells. "The ADAMTS6 expression did not significantly affect the overall survival of NSCLC patients without the histopathological subtype division (p = 0.4622) or the adenocarcinoma patients (p = 0.2618)." (PMID 38339175, 2024).
ADAMTS6 also shares sentences with these, for which no sentence is quoted: colorectal cancer (2 papers); congenital heart disease (1); hyperprolactinemia (1); infection (1); intestinal type adenocarcinoma (1); keratoconus (1); kidney chromophobe (1); Paranoia (1); prion disease (1); renal carcinoma (1); renal cell carcinoma (1); sarcoma (1); schizophrenia (1); skin cutaneous melanoma (1); uterine corpus endometrial carcinoma (1); Weill-Marchesani syndrome (1).